EZH2 (enhancer of zeste 2 polycomb repressive complex 2 subunit)
Diseases named in the same sentence as EZH2 in open-access papers (continued):
Sharing a sentence is not in itself a finding about the gene and the disease.
diffuse large B-cell lymphoma (continued). "In EZH2-resistant cells, EZH2 inhibitors such as GSK126 and tazemetostat fail to inhibit the development of diffuse large B-cell lymphoma (DLBCL) cells, with a significant reduction of apoptosis." (PMID 37909018, 2023). "By maintaining EZH2 protein levels, USP21 promotes cell proliferation and metastasis in bladder carcinoma and cell proliferation in diffuse large B-cell lymphoma." (PMID 35846989, 2022). "For instance, mutations within EZH2, a histone methyltransferase that mediates repression of gene transcription via H3K27, have been reported to be associated with diffuse large B-cell lymphoma (DLBCL)." (PMID 35327559, 2022). "In diffuse large B-cell lymphoma, CDK12 activated MYC to inhibit miR-28-5p/EZH2 and amplify BCR signaling to promote its progression." (PMID 36463205, 2022). "The fact that BCL6 and EZH2 cooperate to repress transcription leads to concurrent inhibition of EZH2 and BCL6 in diffuse large B cell lymphoma." (PMID 36377663, 2022). "Chromatin immunoprecipitation (ChIP) experiments confirmed that EZH2 binds to the CDKN1A promoter in primary human GC B cells and diffuse large B cell lymphoma (DLBCL) cell lines, with concordant enrichment of its H3K27me3 repressive mark." (PMID 29026085, 2017). "Recurrent heterozygous mutations that target specifically Y641 in the SET catalytic domain within the S-adenosylmethionine (SAM) pocket of EZH2 were described in germinal center B-cell diffuse large B-cell lymphoma (GCB DLBCL) and in FL and are found in 22% of patients." (PMID 26497210, 2016). "EZH1/EZH2 dual inhibitors, for example, UNC1999, which is an effective autophagy inducer, has been reported to reduce the diffuse large B-cell lymphoma cell survival, and Valemetostat (DS-3201, DS-3201b) is particularly efficient against adult T-cell leukemia lymphoma cells (ATL cells)." (PMID 39769907, 2024). "Tazemetostat, the histone methyltransferase (HMT) inhibitor of enhancer of zeste homologue 2 (EZH2), is currently in a single agent open-label, phase 1/2 trial in patients with B-cell lymphomas and in combination with prednisolone in diffuse large B-cell lymphoma (DLBCL) (NCT01897571)." (PMID 35710782, 2022). "It was reported that the cooperation of EZH2 and E2F1 in transcriptional activation is conserved in diffuse large B cell lymphomas, which inspired us to investigate whether such cooperation is conserved across species." (PMID 32093739, 2020). "To study the impact of EZH2 inhibition on the genome-wide distribution of H3K27me3, we treated two different human cancer cell lines, KARPAS-422 germinal center B-cell like diffuse large B-cell lymphoma and PC9 lung adenocarcinoma, with different EZH2 inhibitors, CPI-360 and GSK126." (PMID 27875550, 2016). "A single tyrosine 641 (Tyr641) in the SET domain of EZH2 is replaced in 7.2% follicular lymphoma (FL) and 21.7% germinal center B-cell-like (GCB) subtype diffuse large B-cell lymphoma (DLBCL)." (PMID 33761979, 2021). "Here we present a novel highly selective EZH2 inhibitor SHR2554 and possible combination strategy in diffuse large B-cell lymphoma (DLBCL)." (PMID 34503063, 2021). "On the other hand, EZH2 inhibitors impair the occurrence of ferroptosis by upregulating the heat shock protein family A member 5 (HSPA5) and stabilizing GPX4 in diffuse large B-cell lymphoma (DLBCL)." (PMID 39595619, 2024). "Treatment of a diffuse large B-cell lymphoma (DLBCL) cell line which contains the Y641N mutant EZH2 with UNC1999 for 8 days resulted in a potent antiproliferative effect, which is not observed following treatment with UNC2400, a related molecule which is much less active as an EZH2 inhibitor." (PMID 26397018, 2015).
colon carcinoma (117 papers, 2009 to 2025). "EZH2 inhibitors have been used to treat colon cancer because they cause tumor cells to respond to them more frequently (stage II and III)." (PMID 38361095, 2024). "Related, our recent investigation revealed additional role for VprBP in phosphorylating EZH2 in colon cancer cells and established another epigenetic process underlying VprBP-induced oncogenic gene silencing program." (PMID 37293029, 2023). "Related to this, our recent investigation revealed an additional role for VprBP in phosphorylating EZH2 in colon cancer cells and established another epigenetic process underlying a VprBP-induced oncogenic gene silencing program." (PMID 37760992, 2023). "In colon cancer, EZH2 biochemically associates with β-catenin and the PCNA-associated factor PAF to induce the expression of Wnt target genes." (PMID 34943970, 2021). "Nevertheless, loss of EZH2 at the tumor invasion front seems to be correlated with a more aggressive phenotype of cancer cells in colon cancer patients." (PMID 31317325, 2019). "Loss of EZH2 and mitotic activity at the invasion front of colon cancer seems to play an important role for the acquisition of mesenchymal characteristics that are required for the migration and invasion of disseminating tumor and cancer stem cells." (PMID 31317325, 2019). "Recent studies that used colon cancer cell lines have reported that EZH2 expression was inversely associated with microRNA-506, microRNA-26a, and let-7b; these microRNAs downregulated EZH2 expression by directly targeting 3′-UTR." (PMID 26871294, 2016). "A significant dose- and time-dependent decrease in colon cancer cell viability was observed, which was associated with a reduction in EZH2 protein expression (left) and a marked reduction in tri-methylated lysine 27 (H3K27-3me) (right)." (PMID 25611389, 2015). "In a previous study, we have shown that curcumin induced a cytotoxic effect in colon cancer cells, which correlated with the downregulation of Histone Lysine Methyltransferases (KMTs) such as EZH2, G9a, and MLL-1." (PMID 40807229, 2025). "A very recent study demonstrated DCAF1-mediated phosphorylation of EZH2 at T367 to augment its nuclear stabilization and enzymatic activity in colon cancer cells." (PMID 40289112, 2025). "The results of our HPA database study show that EZH2 is highly expressed in colon cancer, which is consistent with our findings." (PMID 40535805, 2025). "To further assess the role of these lncRNAs in other cell types, we performed RIP in HCT116 cells, a human colon cancer cell line, using the H3K27me3 and EZH2 antibodies, respectively." (PMID 39083617, 2024). "In colon cancer, SNHG1/miR-154-5p/EZH2 regulatory axis promotes the growth of colon cancer cells by regulating cell cycle-related signaling pathways." (PMID 38811958, 2024). "This regulatory mechanism of EZH2 is also present in colon cancer and can be inhibited by the H3K27 demethylase Jmjd3." (PMID 39080807, 2024). "Subsequently, in the assays of cell cycles and apoptosis, we found that interference with EZH2 expression significantly increased the apoptosis percentage of colon carcinoma cells." (PMID 38048186, 2023). "Such interpretation is further supported by our assays showing that B32B3 treatment is ineffective at impairing cancer cell growth and H3K27me3 after ectopic expression of EZH2T367D phospho-mimicking mutant in EZH2-depleted colon cancer cells." (PMID 37069142, 2023). "Although our data clearly implicate DCAF1-mediated EZH2T367p in EZH2 stabilization in colon cancer cells, they left open the molecular basis for the observed T367p effects." (PMID 37069142, 2023). "Here the authors show that DCAF1/VprBP phosphorylates and stabilises EZH2 to induce oncogenic gene silencing and colon cancer growth." (PMID 37069142, 2023). "It has been proved that the significantly high expression of EZH2 can promote the proliferation of colon cancer cells." (PMID 36765073, 2023).
colon carcinoma (continued). "In the present study, we show that DCAF1 is overexpressed and phosphorylates EZH2 in colon cancer cells." (PMID 37069142, 2023). "Since we detected equivalent EZH2 mRNA levels in control and DCAF1-depleted SW620 and Caco2 cells, these results indicate a role for DCAF1 in mediating the stabilization and accumulation of EZH2 protein in colon cancer cells." (PMID 37069142, 2023). "Taken together, these results suggest that PROX1 can recruit EZH2 to the SIRT3 promoter region in colon cancer cells, where EZH2 represses SIRT3 transcription." (PMID 36594098, 2023). "Given the demonstrated reliance of EZH2 stability on DCAF1-mediated T367p and EZH2 function dependent of H3K27me3 in colon cancer cells, it was reasonable to expect greater inhibitory effects of Taz plus B32B3 combination in our assays." (PMID 37069142, 2023). "Previous studies have shown that inhibiting EZH2 or DNMT1 in colon cancer cell lines induces a neural-like differentiation phenotype." (PMID 37537688, 2023). "We now demonstrate that DCAF1 phosphorylates EZH2 at T367 to augment its nuclear stabilization and enzymatic activity in colon cancer cells." (PMID 37069142, 2023). "In our research, with a view to determining the specific EZH2 mechanism in colon cancer cells, we adopted RNA interference technology to reduce EZH2 expression in colon cancer cell lines and then conducted subsequent experiments." (PMID 38048186, 2023). "Our observation of DCAF1-dependent phosphorylation and stabilization of EZH2 at growth regulatory genes suggests a concerted mechanism for the placing of EZH2T367p and H3K27me3 marks in colon cancer cells." (PMID 37069142, 2023). "In an extension of this initial discovery, we also demonstrated that treating colon cancer cells with subtoxic concentrations of EZH2 inhibitor Taz recapitulates the effects of DCAF1 inhibitor albeit somewhat less efficiently." (PMID 37069142, 2023). "Given that DCAF1 and EZH2 levels are significantly correlated among colon tumor samples, we also expected the involvement of DCAF1 in catalyzing EZH2T367p during colonic tumorigenesis." (PMID 37069142, 2023). "Collectively, the present study for the first time demonstrated that the expression of FXR was positively correlated with EZH2 in colon cancer tissues." (PMID 35449124, 2022). "PCAT6 can inhibit apoptosis and promote the progress of colon cancer by forming a complex with EZH2." (PMID 36092924, 2022). "It has been reported that miR-506/EZH2 is deregulated in colon cancer and correlated with proliferation and metastasis." (PMID 35154460, 2022). "Overall, it is proposed herein that activation of the GPCR oncogenes PAR4 and PAR2 potently induce lysine methylation of β-catenin by EZH2, promoting its sustained stability levels in colon cancer." (PMID 35955891, 2022). "We found that the expression of FXR was negatively correlated with enhancer of zeste homolog 2 (EZH2) in colon cancer tissues." (PMID 35449124, 2022). "We firstly analyzed the protein levels of FXR and EZH2 in eight colon cancer cells by western blotting." (PMID 35449124, 2022). "It has been reported that colon cancer metastasis is impaired following miRNA-101 overexpression and is attributed to EZH2 down-regulation and subsequent inhibition of cancer invasion." (PMID 35236381, 2022). "EZH2 is upregulated in PAR-driven tumors as well as in aggressive colon cancer cell lines overexpressing PAR2 and PAR4." (PMID 35955891, 2022). "Like other kinds of gastrointestinal tumors, EZH2 overexpression enhances colon cancer progression and its inhibition by anti-tumor agents such as salinomycin is associated with activation of death receptors." (PMID 35236381, 2022). "Though lots of evidence has proved the therapeutic potential of targeting EZH2 in colon cancer, the effect of EZH2 inhibitors on anti-tumor immunity remains elusive." (PMID 35432300, 2022).
colon carcinoma (continued). "PCAT6 activates the expression of antiapoptotic ARC and inhibits colon cancer cell apoptosis by increasing EZH2 expression." (PMID 34692467, 2021). "In colon cancer cells, the PCNA-associated factor (PAF) and EZH2 were shown to induce hyperactivation of WNT signaling." (PMID 33327550, 2020). "Regulation of EZH2 functions by its O-GlcNAcylation has been evidenced in several studies conducted in different cell lines including breast and colon cancer cells." (PMID 33126652, 2020). "In our hands, O-GlcNAcylation does not seem to affect either stability or catalytic activity of EZH2 but appears to regulate the binding of EZH2 at specific loci including the UNC5A promoter in colon cancer cells." (PMID 33126652, 2020). "So, taken together, our overall results demonstrate that in colon cancer cells, O-GlcNAcylation of EZH2 targets the PRC2 complex onto the UNC5A promoter to inhibit its transcription." (PMID 33126652, 2020). "Here, we extended this role of HOTAIR to colon carcinoma cells conferring a more general value to the mechanism of how EZH2 gets to its genomic targets in epithelial cells undergoing EMT." (PMID 30154449, 2019). "For this reason, we immunohistochemically analyzed EZH2 expression in 105 specimens from colon cancer patients separately for tumor center and invasion front." (PMID 31317325, 2019). "In this study, we analyzed the expression of EZH2 in a cohort of 105 colon cancer patients with a median follow-up of 99.7 months." (PMID 31317325, 2019). "AOM/DSS treatment of Apc1638N/+ mice phenocopied CR+AOM treatment as colonic tumors exhibited pronounced changes in Ki-67, EZH2 and Dclk1 accompanied by infiltration of F4/80+ macrophages, CD3+ lymphocytes and CD3/β-catenin co-localization." (PMID 31040926, 2019). "The loss of TET1 leaves methylated DNA, that is, repressed chromatin, which induces cell migration and E-cadherin repression via EZH2/H3K27me3 in colon cancer cells." (PMID 29853899, 2018). "Polycomb group protein enhancer of zeste homologue 2 (Ezh2) enhances stem cell-like properties in colon cancer by activation of the p21cip1-Wnt/β-catenin signaling pathway, thus leading to cell cycle arrest at the G1/S phase." (PMID 28423536, 2017). "The expression of Ezh2 is reported to be closely related to treatment response and prognosis of colon cancer patients." (PMID 28588641, 2017). "Immunohistochemical analyses have also shown that EzH2 is significantly overexpressed in colon cancers when compared to adjacent normal tissue or benign colon adenoma." (PMID 29285251, 2017). "In colon cancer and poorly differentiated synovial sarcomas, EZH2 expression was significantly related to increased tumor cell proliferation, as assessed using the Ki-67 expression." (PMID 28241804, 2017). "A line of evidence showed that Ezh2 played key role in stimulating cell growth and proliferation in colon cancer." (PMID 28588641, 2017). "miR-506 inhibited the proliferation and metastasis of colon cancer via binding to the 3′-UTR of enhancer of zeste homolog 2 (EZH2), a member of the Polycomb group (PcG) protein family." (PMID 27542202, 2016). "Restoration of EZH2 expression partially alleviated the effects of miR-506-overexpressing colon cancer cells." (PMID 27542202, 2016). "An interesting finding in this work is that LDM is relatively more potent in colon cancer cells carrying endogenously high EZH2 expression, and can selectively deplete EZH2 instead of other histone lysine methyltransferases." (PMID 27882937, 2016). "We further tested EZH2 expression in eight paired samples (colon cancer versus adjacent samples) from cancer patients in Zhongshan hospital with immunoblotting (IB) analysis." (PMID 27882937, 2016). "In this exploratory study, we investigated the response of a panel of twenty well-characterized human CRC organoid lines derived from colon cancers to treatment with the EZH2 inhibitor GSK126 over a course of multiple weeks." (PMID 27634879, 2016).
colon carcinoma (continued). "More recently, it has been shown that EZH2 controls cofilin activity and consequently the actin cytoskeleton, regulating integrin alpha 2 expression in colon cancer cells." (PMID 27248655, 2016). "In functional analysis, we showed that the siRNA knockdown of EZH2 increased miR-31 expression in colon cancer cell lines." (PMID 26871294, 2016). "Here, we demonstrate how organoids derived from different colon tumors are affected by EZH2 inhibition and highlight several molecular features that associate with response." (PMID 27634879, 2016). "We first performed immunohistochemistry (IHC) staining to analyze EZH2 expression in human colon cancer tissue array containing 90 primary clinical samples with both tumoral and adjacent normal tissues." (PMID 27882937, 2016). "In our study, we found that miR-506 expression was down-regulated in colon cancer tissue and inversely correlated with EZH2 expression, tumor size, lymph node invasion, TNM stage and metastasis." (PMID 26452129, 2015). "The MTT, Matrigel invasion and wound-healing assays demonstrated that the restoration of EZH2 expression significantly ameliorated the miR-506-induced suppression of colon cancer cell proliferation, invasion and migration, respectively." (PMID 26452129, 2015). "The restoration of EZH2 expression partially reversed the proliferation and invasion of miR-506-overexpressing colon cancer cells." (PMID 26452129, 2015). "The abrogation of EZH2 expression impairs the ability of colon cancer cells to move, resulting in anoikis, in a three-dimensional environment." (PMID 26452129, 2015). "In vitro and in vivo experiments confirmed that miR-506 inhibits the proliferation and metastasis of colon cancer, and a luciferase reporter assay confirmed that EZH2 is a direct and functional target of miR-506 via the 3′UTR of EZH2." (PMID 26452129, 2015). "Some studies have reported that silencing EZH2 expression inhibited the proliferation and invasion of colon cancer cells." (PMID 26452129, 2015). "Here, we demonstrated that miR-506 was down-regulated in colon cancer tissue and cells and that miR-506 expression was inversely correlated with EZH2 expression, tumor size, lymph node invasion, TNM stage and metastasis." (PMID 26452129, 2015). "Further study demonstrated that EZH2 is a direct target gene of miR-506 that suppresses the growth and metastasis of colon cancer via the epigenetic modulation of specific downstream genes and the inhibition of the Wnt signaling pathway." (PMID 26452129, 2015). "To evaluate the correlation of miR-506 and EZH2 expression with the invasiveness of colon cancer, we detected their expression levels in colon cancer cells via qRT-PCR and Western blot." (PMID 26452129, 2015). "The results suggested that the level of miR-506 negatively correlated with the invasiveness of colon cancer cells but that the expression of EZH2 positivity correlated with the invasiveness of colon cancer cells (p < 0.05)." (PMID 26452129, 2015). "We previously transfected HCT116 colon carcinoma cells with a short hairpin RNA (shRNA) vector carrying a stem loop oligonucleotide against EZH2 mRNA." (PMID 25549357, 2014). "For example, enhancer of zeste homolog 2 (EZH2), which encodes the H3K27 HMT, is overexpressed in solid tumors such as breast, skin, prostate, lung, and colon cancer." (PMID 23162793, 2012). "siRNA-treatment resulted in a strong reduction of EZH2 levels in all tested colon carcinoma cell lines and, as previously reported for other cells, in a concomitant decrease of cyclin D1 expression." (PMID 21765901, 2011). "RNA interference (RNAi)-mediated intracellular EZH2 depletion led to cell cycle arrest of colon carcinoma cells at the G1/S transition." (PMID 21765901, 2011). "Previous studies have shown that EZH2 is significantly overexpressed in colon cancers when compared to normal colon tissue." (PMID 21765901, 2011).